IRS1 (insulin receptor substrate 1)
Diseases named in the same sentence as IRS1 in open-access papers (continued):
Sharing a sentence is not in itself a finding about the gene and the disease.
Insulin resistance (continued). "Several studies suggest an important role of IRS-1 S-nitrosylation in insulin resistance through the degradation of IRS1 via the ubiquitin-proteasome pathway." (PMID 37455926, 2023). "For example, maternal obesity results in male offspring hyperinsulinemia and insulin resistance by 3 months of age, accompanied by increased phospho-IRS1 S307 (decreased insulin signaling activity) and reduced phospho-Akt S473 in the offspring liver." (PMID 37855320, 2023). "TNF induces insulin resistance in adipocytes by inhibiting insulin-induced IRS1 tyrosine phosphorylation and insulin-induced glucose uptake." (PMID 36818229, 2023). "In a previous study, Liu and co‐workers showed that quercetin and EGCG improved insulin resistance and hepatic gluconeogenesis via the IRS1/Akt/FOXO1 axis and involving miR‐27a‐3p and miR‐96–5p." (PMID 37329278, 2023). "For example, increased levels of circulating miR-222 were related to the presence of insulin resistance as well as decreased expression of IRS1 in adipose tissue." (PMID 38132872, 2023). "The phosphorylated JNK (p-JNK) and IKK1/1KK2 further attenuate IRS-1 S307 residue phosphorylation, thereby suppressing insulin signaling activation to induce insulin resistance." (PMID 37555019, 2023). "Progesterone is implicated in insulin resistance by inhibiting the PI3-kinase pathway, and insulin receptor substrate 1 (IRS1) expression." (PMID 36631877, 2023). "Further correlation analysis showed that the activation of BAT thermogenesis promotes peripheral glucose and lipid metabolism, regulates insulin resistance, and has a positive effect on IRS-1 upregulation." (PMID 38283741, 2023). "MUFA induced insulin resistance in the liver and skeletal muscle by increasing serine phosphorylation of the β-subunit of the insulin receptor substrate-1 (IRS-1), inhibiting insulin signaling in the insulin cascade, and promoting insulin resistance." (PMID 37764688, 2023). "An increased amount of GLUT-4 in adipose tissue is a good marker of systemic insulin sensitivity and decreased level of IRS-1 was reported to be involved in insulin resistance." (PMID 37447192, 2023). "In the skeletal muscle of rats with vast fructose supplement, curcumin alleviated insulin resistance by reducing Insulin receptor substrate (IRS-1) serine phosphorylation and IRS-1 tyrosine phosphorylation." (PMID 37191432, 2023). "Knockdown of METTL4 led to downregulation and inactivation of the INSR pathway, thereby regulating the IRS-1/PI3K/AKT pathway to improve insulin resistance." (PMID 37998047, 2023). "For example, TNF-α/tumor necrosis factor receptor 1 (TNFR1)/IRS-1 signaling is one of the most important regulatory axes for insulin resistance." (PMID 37555019, 2023). "The researchers observed that ASX reduced the production of nitric oxide (NO), leading to a reduction in insulin resistance through increased serine phosphorylation of insulin receptor substrate 1 (IRS1)." (PMID 38004197, 2023). "Both can be activated by the insulin/insulin receptor substrate‐1 (IRS1) system in insulin resistance." (PMID 36333974, 2023). "By reducing intracellular lipid accumulation and preventing lipid-induced, PKCθ-mediated degradation of IRS1/2, aM1 restores glucose uptake to overcome insulin resistance." (PMID 37715850, 2023). "The expression levels of INSR, IRS-1 and p-IRS-1 in the liver and skeletal muscle of HF group mice decrease gradually with the progress of insulin resistance, while those in the ovary organ present the opposite trend." (PMID 37830511, 2023). "This is consistent with other studies that found elevated levels of IRS-1 pSer307, pSer312, and pSer616 connected with neuronal insulin resistance in AD." (PMID 35164216, 2022). "Different studies have demonstrated that miR-126 decreases VCAM-1 expression and can promote insulin resistance by inhibiting IRS-1." (PMID 36139749, 2022).
Insulin resistance (continued). "To characterize insulin resistance due to altered signaling through IRS-1, we employed obese Zucker rats (OZRs), a well-studied genetic model of insulin resistance that exhibits marked hyperinsulinemia due to a leptin receptor mutation." (PMID 36547071, 2022). "Excessive chronic IL-6 production promotes the development of insulin resistance and T2D by impairing the phosphorylation of IR and IRS-1 via the upregulation of SOCS-3 (suppressor of cytokine signaling 3), a potential inhibitor of insulin signaling." (PMID 35629988, 2022). "Taken together, these results suggest that aerobic exercise ameliorates insulin resistance in skeletal muscle and that the IRS-1/PI3K/AKT/GLUT4 pathway plays a role in glucose metabolism." (PMID 36145106, 2022). "They observed that the increased O-GlcNAc modification of IRS-1 and Akt2 reduced the insulin-stimulated phosphorylation of IRS-1 and Akt2, which induced insulin resistance characterized by prominently decreased GLUT4 translocation in adipocytes." (PMID 36005597, 2022). "IRS-1 genetic variations have a deleterious effect on insulin resistance, reduced ability to store subcutaneous fat, and disrupted insulin signalling in liver and muscle, resulting in ectopic deposition of lipids." (PMID 36035124, 2022). "Decreased expression of IRS-1 and 2 and decreased phosphorylation of Akt and eNOS are key hallmarks of vascular insulin resistance." (PMID 35055038, 2022). "JNK is responsible for ER stress induced insulin resistance through promotion of serine/threonine phosphorylation of IRS1 which results in IRS1 degradation." (PMID 35936891, 2022). "JNK promotes insulin resistance through phosphorylation of serine residues in IRS-1, and IKKβ induces insulin resistance through transcriptional activation of nuclear factor-κB (NF-κB)." (PMID 35625904, 2022). "Together, these data show that palmitate inhibits insulin-induced formation of endogenous IRS1 condensates, which is in parallel with the development of insulin resistance in cells." (PMID 35790738, 2022). "Central insulin resistance mediated by serine phosphorylation of insulin receptor substrate-1 (IRS-1) has been shown to play a critical role in AD." (PMID 35453480, 2022). "The activation of such molecular mediators promotes the disruption of the insulin signaling pathway, mainly by serine phosphorylation of IRS-1 that leads to insulin resistance and a glucose uptake blockade." (PMID 35327570, 2022). "The authors reported a decreased expression in insulin receptor (IR-β) and insulin receptor substrate (IRS-1), leading to insulin resistance." (PMID 36077184, 2022). "For example, the phenylsulfamide fungicide tolylfluanid has been shown to induce cellular insulin resistance in primary murine and human adipocytes by reducing insulin receptor substrate-1 (IRS-1) expression and stability." (PMID 35466213, 2022). "Consistently, our data showed that P3HA3knockdown can improve insulin resistance by activating IRS-1/PI3K/Akt/FoxO1signaling pathway." (PMID 35976267, 2022). "IRS-1 phosphorylation at specific serine residues disrupts PI3K/Akt coupling to IGF-1 and IR, leading to IRS-1 inactivation and degradation, which is a feature of brain insulin resistance (IRes)." (PMID 35164216, 2022). "Free radicals downregulate protein kinase B (Akt), insulin receptor substrate-1 (IRS-1), and glycogen synthase kinase 3 (GSK-3), lowering insulin sensitivity and causing insulin resistance." (PMID 35883721, 2022). "MiR-103a-3p is found in adipose tissue cells, regulating mRNA expression, and causing insulin resistance by altering GLUT4, IRS-1 and caveolin-1 (cav-1)." (PMID 36432399, 2022).
Insulin resistance (continued). "TNFα, a regulated product of NF-κB and a strong activator of NF-κB, induces insulin resistance mainly through serine phosphorylation of insulin receptor substrate-1 (IRS1)." (PMID 36510592, 2022). "This study reveals the crucial role of miR-183-5p in the insulin signaling pathway by targeting IRS-1 and suggests a novel mechanism for hepatic insulin resistance in obesity." (PMID 35328400, 2022). "On the other hand, there are reports that ROSs are involved in the mechanism of insulin resistance, and the mechanism was reported that chronic increase in ROSs led to phosphorylation of IRS-1 and decreased translocation of GLUT4 to the membrane." (PMID 35883894, 2022). "BM-MSCs infusion ameliorated insulin resistance of rats with T2DM by activating the insulin receptor substrate 1/protein kinase B signaling pathways." (PMID 35505375, 2022). "β-arrestin 1 can alter insulin signaling by inhibiting insulin-induced proteasomal degradation of IRS-1 and the inhibition of beta-arrestin-1 leads to enhanced IRS-1 degradation and accentuated cellular insulin resistance." (PMID 35430346, 2022). "FFA is an effective activator of JNK, and FFA induces insulin resistance by inhibiting the serine phosphorylation of IRS-1." (PMID 35509833, 2022). "In order to assess the correlation between insulin resistance and tau pathology, we selectively analyzed the individuals with the highest and lowest levels of the p-IRS-1(Ser616) and p-Tau(Thr231)." (PMID 35563135, 2022). "ER stress-induced insulin resistance is mediated by activation of c-Jun N-terminal kinase (JNK) which promotes serine/threonine phosphorylation of insulin receptor substrate-1 (IRS1) resulting in IRS1 degradation." (PMID 35936891, 2022). "We found that neddylation and subsequent activation of cullin-RING ligase complexes induced synaptic insulin resistance through ubiquitylation and degradation of the insulin-receptor substrate IRS1 that organizes synaptic insulin signaling." (PMID 34986876, 2022). "For example, an increase in TNF-α reduces the secretion of adiponectin and promotes insulin resistance by the inhibition of the insulin receptor substrate 1 signaling pathway." (PMID 35956908, 2022). "In adipose tissue in obesity, the activation of this pathway results in insulin resistance through IKK-mediated serine phosphorylation of IRS-1 or insulin receptor, leading to the inhibition of insulin-induced serine phosphorylation and downstream signaling." (PMID 36012516, 2022). "Despite the fact that our result did not determine the expression of phosphorylation of the IRS-1 and GLUT4, the decreased protein expressions of IRS-1 can demonstrate the insulin resistance in skeletal muscle." (PMID 36235772, 2022). "We observed a WD-derived increase in the level of p-IRS-1(Ser616) in the entorhinal cortex, which indicates the development of insulin resistance." (PMID 35563135, 2022). "The activation of JNK promotes the phosphorylation of insulin receptor substrate (IRS-1) at serine residues that leads to negative regulation of insulin signal transduction and induces insulin resistance." (PMID 35454131, 2022). "We evaluated the effects of mulberry leaves extract (MLE) and 1-deoxynojirimycin (1-DNJ) in improving insulin resistance through the activation of the IRS-1/PI3K/Akt pathway in the skeletal muscle of db/db mice." (PMID 36295064, 2022). "Genes associated with type 2 diabetes mellitus, insulin resistance, hyperinsulinemia, adiposity, and CAD are located adjacent to the IRS1 gene, which possesses common genetic variation." (PMID 36292779, 2022). "A high fat diet induced insulin resistance, by reducing the expression of IRS-1, which is an important mediator in insulin signal pathway." (PMID 35487948, 2022). "An increase in insulin receptor substrate 1, a candidate biomarker of brain insulin resistance, was found in MCI and AD patients, providing an additional link between AD pathology and insulin resistance." (PMID 35741464, 2022).
Insulin resistance (continued). "This substitution has effects on the tertiary structure of IRS-1 and results in disturbed downstream signaling and finally can lead to impaired glucose tolerance and insulin resistance." (PMID 36011374, 2022). "Our data reveal a previously-unrecognized mechanism for IRS1 to mediate insulin signaling and to confer insulin resistance, which involves LLPS-mediated formation of IRS1 condensates." (PMID 35790738, 2022). "Tumor necrosis factor-α induced phosphorylation of insulin receptor substrate 1 (IRS-1), preventing insulin from binding to the receptor, which consequently led to insulin resistance." (PMID 35433780, 2022). "Other mechanisms of insulin resistance include the reversion of the insulin-induced tyrosine phosphorylation of IRS-1, IRS degradation and decreased GLUT-4 expression." (PMID 35327570, 2022). "The liver insulin IRS1/PI3K/AKT signaling pathway is of great significance in improving hepatic insulin resistance." (PMID 36676939, 2022). "Mechanistically, downstream of RhoA/ROCK-mediated F-actin assembly, nuclear translocation of MRTF-A suppresses the expression of IRS1 and PPARγ in hypertrophic adipocytes, contributing to adipocyte dysfunction and insulin resistance." (PMID 35769086, 2022). "One of the targets to induce insulin resistance and IRS-1 at a low ebb is viewed in obese and insulin-resistant individuals." (PMID 36235831, 2022). "First, uric acid induces insulin resistance by inhibiting intrahepatic IRS1 and Akt insulin signaling, which promotes the liver fat accumulation." (PMID 36079844, 2022). "Insulin receptor substrates include insulin receptor substrate-1 (Irs1) and insulin receptor substrate-2 (Irs2), and Irs1 and Irs2 double knockout mice developed liver insulin resistance, which resulted in hyperinsulinemia and diabetes." (PMID 35242879, 2022). "Phosphorylation of Ser/Thr-residues of IR and IRS-1 proteins constitutes an essential factor contributing to the development of insulin resistance." (PMID 35682723, 2022). "Available studies have indicated that HCV core protein expression induces hepatic insulin resistance by altering the signaling pathway of the insulin receptor substrate-1." (PMID 35893594, 2022). "First, the autocrine action of SDF1 on adipocytes is reported to induce inhibitory IRS1 phosphorylation and result in insulin resistance in mice." (PMID 35563078, 2022). "Consistent with previous studies, the results showed that UMSC-EXOs derived hsa_circ_0046060 repressed IRS-1 activation, resulting in insulin resistance." (PMID 35726320, 2022). "The increased level of IRS-1, due to curcumin, was found to be responsible for the alleviation of insulin resistance." (PMID 35807304, 2022). "Altogether, these induce insulin resistance by promoting serine-phosphorylation of IRS-1, which impairs insulin signaling and subsequently inhibits glucose uptake by target cells." (PMID 36434695, 2022). "CTPG ameliorated HFD-induced hyperinsulinemia, hyperglycemia, inflammation and insulin resistance by activating IRS1/Akt/GLUT4 insulin signaling pathway in white adipose tissue." (PMID 36229811, 2022). "Neutrophils also secrete NE, which impairs the energy expenditure in the adipose tissue) and promotes insulin resistance by degrading insulin receptor substrate 1 (IRS-1)." (PMID 35741012, 2022). "Palmitic acid can impair the insulin signaling pathway, IRS/P13K/Akt, promoting IR, IRS-1, and Akt ubiquitination and subsequent protein degradation, leading to insulin resistance." (PMID 36035400, 2022). "It was also observed in HCV core transgenic mouse model that the core protein-induced serine phosphorylation of IRS-1 stimulates insulin resistance and decreases glucose uptake." (PMID 36466918, 2022).
Insulin resistance (continued). "They trigger NF-κB and AP-1, produce IL-6 and TNF-α that affect insulin sensitivity by altering the expression of genes encoding IRS-1, GLUT-4, and PPAR-α and lead to insulin resistance." (PMID 36140983, 2022). "Overexpressing Ddr2 in 3T3-L1 adipocytes leads to reduction of insulin-stimulated IRS-1 tyrosine phosphorylation and glucose transporter, thereby insulin resistance." (PMID 34645939, 2022). "On the other hand, Plin5 can reduce the activity of the JNK pathway and reduce the inhibition of IRS-1, thus achieving the effect of improving insulin resistance." (PMID 35509833, 2022). "Biochemical studies have confirmed that IRS-1 phosphorylation is the target of JNK-mediated insulin resistance." (PMID 35509833, 2022). "Proinflammatory cytokines can induce insulin receptor substrate-1 serine phosphorylation and block the insulin signalling pathway; thus, they are considered the dominant factor in the development of insulin resistance." (PMID 36324119, 2022). "IRS1 and IRS2 are vital components of insulin signaling, and the loss of IRS1 and IRS2 mediates insulin resistance." (PMID 35454166, 2022). "JNK is a serine/threonine kinase shown to increase serine phosphorylation of IRS-1 and is involved in insulin resistance." (PMID 35011728, 2022). "On the other hand, it has been found that IR/IRS-1-Ser/Thr-phosphorylation represents a critical factor promoting the development of insulin resistance and accelerates their degradation." (PMID 35682723, 2022). "Tumor necrosis factor (TNF) is mainly secreted by macrophages and can induce insulin resistance through inhibition of Insulin receptor substrate 1 (IRS1), tyrosine phosphorylation and G kinase-anchoring protein 1 (GKAP42) degradation in adipocytes." (PMID 36457705, 2022). "The same trend was observed in the level of IRS-1, whose activation was impaired by increased phosphorylation at Ser612, the phosphorylation connected to insulin resistance." (PMID 36126192, 2022). "In mice fed with a high-fat diet, Angptl4 overexpression alleviated glucose intolerance and insulin resistance by promoting insulin signaling via IRS-1 phosphorylation." (PMID 36292250, 2022). "Evidence indicates that serine phosphorylation of IRS-1 leads to impaired insulin signaling and contributes to insulin resistance." (PMID 35011728, 2022). "When insulin resistance affects the binding of IRS-1 to the receptor, it leads to reduced glucose trafficking and phosphorylation and decreased NO endothelial function." (PMID 35454166, 2022). "An increase in IRS-1 inhibitory serine phosphorylation instead of tyrosine phosphorylation is a marker of insulin resistance." (PMID 36499613, 2022). "We show that H19 regulates the levels of HDAC6 within the cell and this regulation consequently determines IRS1 levels and insulin resistance in the skeletal muscle." (PMID 35842608, 2022). "STAT3 induces insulin resistance in muscles by leading to degradation of IRS-1 through the upregulation of F-Box Protein 40 (Fbxo40), a muscle-specific E3 ubiquitin ligase." (PMID 35454131, 2022). "Both hyperglycaemia and insulin resistance can downregulate IRS-1, which is a pivotal intermediary in insulin/IGF-1 signalling." (PMID 36035124, 2022). "In this study, we found a significant increase p(Ser)-IRS1 in PH-Tau-Tg mice compared to controls, indicating alteration in IR signal transduction and some levels insulin resistance." (PMID 35264925, 2022). "In obese people, IL-6 reduces the expression of glucose transporter-4 (GLUT4) and insulin receptor substrate-1 (IRS-1) and, thus, increases insulin resistance." (PMID 36013196, 2022). "Another primary reason for insulin resistance is an altered serine/threonine phosphorylation of IRS-1 by a large number of protein kinases, a critical event explaining the molecular basis of the down-regulation of insulin signaling." (PMID 36547071, 2022).